NECTIN4 (nectin cell adhesion molecule 4)
Diseases named in the same sentence as NECTIN4 in open-access papers (continued):
Sharing a sentence is not in itself a finding about the gene and the disease.
gastric cancer (12 papers, 2019 to 2025). A primary or metastatic malignant neoplasm involving the stomach. "Higher NECTIN4 expression was associated with poorer prognosis of gastric cancer and papillary thyroid cancer, and the progression of cancer was promoted by NECTIN4 via activation of the PI3K/Akt pathway." (PMID 33478111, 2021). "Nectin-4, as a cell adhesion molecule highly expressed in gastric cancer, offers a new direction for cross-tumor translational therapy in gastric cancer." (PMID 41361128, 2025). "Based on the excellent tumor penetration capabilities inherent in nanobodies (Nbs), we developed Nectin-4-targeting Nb drug conjugates (NDCs) for the treatment of gastric cancer." (PMID 38755613, 2024). "To acquire a more profound understanding of the in vivo targeting efficacy of Nectin-4 NDC, we conducted in vivo fluorescence imaging of Nectin-4 NDC in 6 BALB/c nude mice bearing NCI-N87 human gastric cancer xenografts." (PMID 38755613, 2024). "In this study, we devised an innovative humanized trivalent Nb-based NDC targeting Nectin-4 and assessed its therapeutic efficacy in a human gastric cancer model." (PMID 38755613, 2024). "Our Nectin-4 NDC effectively inhibited gastric cancer growth in vivo in a dose-dependent manner, indicating its potential as an effective anti-tumor agent for gastric cancer and other Nectin-4-positive tumors." (PMID 38755613, 2024). "Strong expression of Nectin-4 is associated with high disease control rate (DCR), and high expression of Nectin-4 in other cancers, including NSCLC, hepatocellular carcinoma, and gastric cancer, has been associated with poor patient outcomes." (PMID 38606099, 2024). "Subsequent administration of Nectin-4 NDC to mice bearing NCI-N87 human gastric cancer xenografts demonstrated rapid tissue penetration and high tumor uptake through in vivo imaging." (PMID 38755613, 2024). "We further utilized H&E staining and immunohistochemistry to study the morphological changes induced by Nectin-4 NDC in gastric cancer." (PMID 38755613, 2024). "In gastric cancer higher Nectin 4 expression was found in cancerous compared to normal gastric tissues and was associated to unfavorable outcome." (PMID 31137558, 2019). "However, there is limited research on Nectin-4 ADCs specifically for gastric cancer, and conventional immunoglobulin G (IgG)-based ADCs frequently encounter binding site barriers." (PMID 38755613, 2024). "Our in vivo experiments yielded promising results, suggesting that the Nectin-4 NDC could be an effective strategy for treating gastric cancer." (PMID 38755613, 2024). "In gastric cancer high Nectin-4 expression was associated with higher tumor stage, lymph node metastases and poorer grading." (PMID 36268557, 2022). "Therefore, Nectin-4 holds promise as a hopeful therapeutic target for gastric cancer." (PMID 38755613, 2024). "Nectin-4, as a cancer biomarker, has been elucidated to be intricately associated with lymph node metastasis mediated through the PI3K/AKT pathway, ultimately leading to an unfavorable prognosis, with its expression closely correlated with different TNM stages of gastric cancer." (PMID 38755613, 2024). "We have engineered a Nectin-4 NDC with elevated affinity and effective tumor uptake, further establishing its potential as a therapeutic agent for gastric cancer." (PMID 38755613, 2024). "In the context of in vivo efficacy assessments, Nectin-4 NDC demonstrated remarkable tumor inhibitory effects, suggesting its potential as a treatment for gastric cancer." (PMID 38755613, 2024). "Leveraging Nb, we developed a novel Nectin-4-targeting NDC and evaluated its anti-tumor efficacy against gastric cancer." (PMID 38755613, 2024). "Following the in vivo distribution study, we proceeded to evaluate the in vivo efficacy of Nectin-4 NDC, utilizing BALB/c nude mice bearing NCI-N87 human gastric cancer xenografts." (PMID 38755613, 2024).
gastric cancer (continued). "However, in our in vitro efficacy studies, Nectin-4 NDC did not exhibit 100% cytotoxicity on NCI-N87 gastric cancer cells expressing Nectin-4." (PMID 38755613, 2024).
breast tumors (10 papers, 2007 to 2025). "Soluble Nectin4 was detected both in the supernatant of breast tumor cell lines and in 51% of the sera of patients with metastatic breast carcinoma." (PMID 36457999, 2022). "NECTIN2 and NECTIN4 secreted by BCSC interacted with CD96 and TIGIT on immune cells, causing T-cell inhibition and immune escape at primary breast tumors." (PMID 34611125, 2021). "In 2394 patient tumor specimens, nectin-4 was overexpressed in 60% and 53% of bladder and breast tumor tissues, respectively." (PMID 34358100, 2021). "It is possible to engineer Nectin-4-specific MV to exclusively target and destroy Nectin-4-positive breast tumors and other adenocarcinomas." (PMID 33406633, 2021). "For ovarian and breast tumor cell lines, nectin-4 was overexpressed in 50% (4/8) and 68% (23/34), respectively." (PMID 34358100, 2021). "Nectin4 lies in a region syntenic to human chromosome 1q23.3, and is overexpressed in human bladder and breast tumors, highlighting it’s potential as a drug target for epithelial cancers." (PMID 32209086, 2020). "Nectin-4 expression profile correlates with the expression of markers that define the basal subtype in breast tumors." (PMID 17474988, 2007). "Expression of Nectin-4 protein was measured on a panel of 78 primary cells and cell lines from different origins and 57 breast tumors by FACS analysis and immunohistochemistry (IHC), respectively." (PMID 17474988, 2007). "Expression of Nectin-4 was compared with the expression of protein markers on 52 early stage breast tumors." (PMID 17474988, 2007). "As a common strategy of enhancing monotherapeutic anticancer efficacy, we explored the combinatorial chemovirotherapeutic approach of combining oncolytic measles virus (MV), which targets the breast tumor marker Nectin-4, and the anticancer UA against breast adenocarcinoma." (PMID 33406633, 2021). "TACE is thus mainly responsible for Nectin-4 cleavage in breast tumors." (PMID 17474988, 2007).
squamous cell carcinoma (10 papers, 2007 to 2025). A carcinoma arising from squamous epithelial cells. "One study characterized nectin-4 expression using IHC from radical cystectomy samples among the three most frequent variant subtypes: squamous cell carcinoma, adenocarcinoma, and sarcomatoid UC." (PMID 40225697, 2025). "The median H-score of nectin-4 was the lowest for sarcomatoid UC (10, range 0–185), compared to squamous cell carcinoma (150, range 0–250), and adenocarcinoma (140.5, range 30–275)." (PMID 40225697, 2025). "EV was selected due to the evidence of the high expression of Nectin-4 in squamous cell carcinomas, including penile carcinoma." (PMID 38003302, 2023). "We found a high expression of Nectin-4 in squamous cell carcinoma and adenocarcinoma and a low expression in sarcomatoid urothelial carcinoma." (PMID 36139571, 2022). "Nectin-4 was expressed in the epidermoid carcinoma cell line A431 and the choriocarcinoma cell line BeWo." (PMID 17474988, 2007). "Nectin-4 positivity according to histological type was 68.2% in UC, 70% in squamous cell carcinoma, 66% in adenocarcinoma, 28% in patients with micropapillary variants, 50% in those with nested variants, 63% in those with plasmacytoid variants, and 10% in those with sarcomatoid carcinoma." (PMID 39123376, 2024).
virus infection (10 papers, 2011 to 2024). "Blocking the binding of CDV-H-RBD and functional receptors (SLAM and Nectin-4) at the early stage of virus infection will be an effective approach." (PMID 37215466, 2023). "Cell-free virus infection would be best modelled using SLAM-F1 expressing target cells whereas the spread of virus across epithelial barriers would be modelled better using nectin-4 expressing target cells." (PMID 26706278, 2016). "Of the eight cell lines studied, ABC1, NCI-H441, H2170, H358, and Calu-3 exhibited relatively higher levels of Nectin-4 expression, and cell death was observed for all of these cell lines following virus infection." (PMID 26317644, 2015). "Given that morbilliviruses have evolved two distinct receptor interactions (SLAM-F1 and nectin-4), it may be possible to distinguish antibodies that prevent cell-free virus infection from those that prevent cell-cell spread and dissemination." (PMID 26706278, 2016). "Only PVRL4 (Nectin 4) converted cells that were resistant to measles viral infections, to cells that could support virus infections." (PMID 21901103, 2011). "The viral infection of H513 was not impacted by the addition of blocking antibodies to nectin-4." (PMID 28968974, 2017). "The highly fusogenic F proteins of SSPE viruses support spread of viral infection to receptor-negative cells by cell–cell fusion, a marker of neurovirulence enabling viral propagation in the brain, where the MV receptors, SLAM and nectin 4, are not expressed." (PMID 34643483, 2021).
esophageal cancer (8 papers, 2019 to 2025). A primary or metastatic malignant neoplasm involving the esophagus. "In 94 samples of esophageal cancer, patients with high Nectin-4 expression showed decreased OS (HR = 1.747; 95% CI 1.003–3.044, p < 0.05)." (PMID 36136143, 2022). "In the present study, we aimed to characterize the expression pattern of Nectin-4 in human esophageal cancer (EC) tissues, and to investigate its clinical implications, prognostic value and regulatory effects on cellular functions of EC cells." (PMID 31043861, 2019). "Enfortumab vedotin targets nectin-4, a member of a family of calcium-dependent, immunoglobulin-like adhesion molecules found in adherens junctions and expressed in various epithelial malignancies, including bladder, breast, lung, ovarian, head/neck, and esophageal cancers." (PMID 32542157, 2020).
metastatic disease (8 papers, 2021 to 2025). "In contrast to changes in nectin-4 H-score between primary and metastatic disease, low NECTIN4 amplification in the primary specimen can be potentially used to predict primary resistance in aUC." (PMID 40225697, 2025). "Comparison of Nectin‐4 and ABC transporter expression in primary and metastatic tumours." (PMID 39877564, 2025).
hepatocellular carcinoma (7 papers, 2019 to 2024). A malignant tumor that arises from hepatocytes. "In 87 samples with hepatocellular carcinoma higher Nectin-4 expression was associated with shorter recurrence free survival (17.73 months versus 25.79 months, p = 0.006) and median OS (21.92 months versus 31.32 months, p = 0.005)." (PMID 36136143, 2022). "NECTIN4 mRNA and protein expression are upregulated in hepatocellular carcinoma." (PMID 34925438, 2021). "In hepatocellular carcinoma (HCC) Nectin 4 was over-expressed in 68% HCC tissues and positive Nectin 4 expression was significantly correlated with tumor size, status of metastasis, vascular invasion and tumor-node-metastasis stage." (PMID 31137558, 2019).
melanoma (7 papers, 2021 to 2025). A malignant, usually aggressive tumor composed of atypical, neoplastic melanocytes. "We recently reported that high NECTIN4 expression is associated with a poor prognosis of skin tumors such as extramammary Paget’s disease and malignant melanoma, and suggested the potential of NECTIN4 as a target in skin cancer therapy." (PMID 33808400, 2021). "Mutational activation of BRAF is associated with tumor progression and BRAF-mutated melanoma showed higher NECTIN4 expression than melanoma with wild-type BRAF." (PMID 33478111, 2021). "NECTIN4 was highly expressed in BRAF-mutated melanoma and its high expression was associated with disease-free survival." (PMID 33478111, 2021). "This work uncovers a link between NECTIN4 expression with BRAFV600E mutation and with BRAFi resistance in melanoma, and provides a rationale for using NECTIN4-targeted drugs to treat melanoma with high NECTIN4." (PMID 33478111, 2021). "NECTIN4 was highly expressed in BRAFV600E-mutated melanoma, and its high expression was associated with poor prognosis." (PMID 33478111, 2021). "In this paper, we report for the first time that NECTIN4 is expressed in human melanoma, with an especially higher frequency in BRAF-mutated melanoma." (PMID 33478111, 2021). "NECTIN4 is likely to be associated with the tumor prognosis and plays roles in the progression of melanoma." (PMID 33478111, 2021). "NECTIN4 was shown to be frequently expressed in BRAF-mutated melanoma." (PMID 33478111, 2021). "However, the association between NECTIN4 expression and the progression of melanoma and its function in melanoma is largely unknown." (PMID 33478111, 2021). "HER3 and NECTIN4 are regarded as promising therapeutic targets for various cancers including melanoma." (PMID 40437181, 2025). "Western blotting of the cells demonstrated the protein expression of NECTIN4, which has recently attracted attention as a potential therapeutic target for melanoma." (PMID 40437181, 2025). "In the current study, we examined the expression of HER3 and NECTIN4, which we previously assessed in melanoma." (PMID 40437181, 2025). "A high level of nectin-4 was significantly associated with BRAF mutation and worse DFS, melanoma-specific survival and OS, and therefore also indicated poor prognosis." (PMID 37568798, 2023). "In vitro analyses revealed increased NECTIN4 in the BRAFi-resistant melanoma cells and upregulation of the PI3K/Akt pathway." (PMID 33478111, 2021). "Of note, patients with NECTIN4-high melanoma showed significantly poor disease-free survival (DFS) compared with those with NECTIN4-low melanoma (p = 0.0358)." (PMID 33478111, 2021). "Next, the effects of NECTIN4 inhibition on the sensitivity of melanoma cells to BRAFi were examined." (PMID 33478111, 2021). "Targeted therapies against NECTIN4 can be a novel treatment strategy for melanoma, even after the acquisition of BRAFi resistance." (PMID 33478111, 2021). "In agreement with reports on other tumors, we found that NECTIN4 is expressed in melanoma and its expression reflects a poorer prognosis." (PMID 33478111, 2021). "Taking these findings together, NECTIN4 is suggested to play roles in the progression of melanoma, presumably through activation of the PI3K/Akt signaling pathway." (PMID 33478111, 2021). "Monomethyl auristatin E, a cytotoxic part of NECTIN4-targeted antibody–drug conjugate, was effective for BRAF-mutated or BRAFi-resistant melanoma cells." (PMID 33478111, 2021). "In BRAFi-resistant melanoma cells, NECTIN4 and the PI3K/Akt pathway were upregulated, along with the acquisition of BRAFi resistance." (PMID 33478111, 2021). "Knockdown of NECTIN4 induced apoptosis and improved sensitivity to BRAFi, suggesting the roles of NECTIN4 in the survival of BRAFi-resistant melanomas." (PMID 33478111, 2021). "We aimed to investigate the role of NECTIN4 in melanoma and its potency as a therapeutic target using 126 melanoma samples and BRAFi-resistant cells." (PMID 33478111, 2021).
melanoma (continued). "NECTIN4-targeted therapy with ADCs, such as enfortumab vedotin, is a potential candidate for treating melanoma with BRAF-mutation and BRAFi-resistant melanomas, and its efficacy needs to be assessed in future research." (PMID 33478111, 2021). "We further showed that NECTIN4 was upregulated in BRAFi-resistant melanoma cells compared with their BRAFi-sensitive counterparts." (PMID 33478111, 2021). "Then, NECTIN4 expression in melanoma patients was examined and presented as the H-score (mean: 48.1, range: 0–225, median: 30)." (PMID 33478111, 2021). "We also showed that the silencing of NECTIN4 resulted in the reduction in the proliferation and induction of apoptosis in melanoma cells." (PMID 33478111, 2021). "Additionally, we explored the protein expression of HER3 and NECTIN4, as they are potential therapeutic targets for melanoma and various other skin cancers." (PMID 40437181, 2025). "Nectin-4 showed high positive staining in 35.7% of melanoma samples." (PMID 37568798, 2023). "In conclusion, we revealed the expression and roles of NECTIN4 in melanoma." (PMID 33478111, 2021). "In conclusion, we have investigated the expression and roles of NECTIN4 in melanoma." (PMID 33478111, 2021). "NECTIN4 was expressed in these melanoma cells in both mRNA and protein levels." (PMID 33478111, 2021). "To investigate the NECTIN4 expression in melanoma, we first assessed NECTIN4 in melanoma patients." (PMID 33478111, 2021). "Taking our findings together, we have shown that 1 NECTIN4 is expressed in melanoma patients and in melanoma cells, 2 NECTIN4 is upregulated in response to the acquisition of BRAFi resistance, and 3 melanoma cells are sensitive to MMAE (an anti-mitotic drug that is a component of ADCs)." (PMID 33478111, 2021). "Since NECTIN4 is expressed in melanoma cells, we next examined whether these NECTIN4-expressing melanoma cells are sensitive to MMAE, a cytotoxic part of enfortumab vedotin." (PMID 33478111, 2021). "Although detailed investigation is required, NECTIN4 may partly contribute to the acquisition of drug-resistance and these results imply the potency of NECTIN4 as a target of novel drugs for BRAFi-resistant melanoma." (PMID 33478111, 2021). "Importantly, NECTIN4 was expressed in melanomas and co-expressed with SOX10." (PMID 33478111, 2021). "Taking all results together, the NECTIN4 induction and the subsequent PI3K/Akt pathway activation may cause BRAFi resistance and promote melanoma cell proliferation, suggesting that NECTIN4-targeted therapy may serve as a potent treatment for patients with BRAFi-resistant melanoma." (PMID 33478111, 2021). "As for melanoma-specific survival (MSS) and overall survival (OS), NECTIN4-high patients tended to show shortened survival (p = 0.196 for MSS and p = 0.0733 for OS)." (PMID 33478111, 2021). "Although NECTIN4 is known to regulate the PI3K/Akt pathway in several cancers, such as breast, gastric, thyroid, and melanoma, this pathway was not affected by NECTIN4 inhibition under the present experimental conditions." (PMID 33808400, 2021). "Although the association between BRAFi resistance and NECTIN4 expression has not been reported, we found that the expression of NECTIN4 was increased, along with the acquisition of BRAFi resistance in melanoma cells." (PMID 33478111, 2021). "Even though our results suggest that the NECTIN4-targeting ADCs, such as enfortumab vedotin, exert antitumor effects against melanoma regardless of their BRAF mutation status, even after the melanoma cells develop to acquire BRAFi resistance." (PMID 33478111, 2021). "Considering the NECTIN4 expression in melanoma cells and their sensitivity to MMAE, enfortumab vedotin may act as an effective anti-tumor drug against melanoma, and BRAFi-resistant cells are more likely to be sensitive to it." (PMID 33478111, 2021). "This implies that NECTIN4 might be involved in malignant transformation and drug-resistance development in BRAFV600E-melanomas." (PMID 33478111, 2021).